TET2 (tet methylcytosine dioxygenase 2)
Diseases named in the same sentence as TET2 in open-access papers (continued):
Sharing a sentence is not in itself a finding about the gene and the disease.
breast carcinoma (continued). "Furthermore, Tet2 deletion-PyMT breast cancer mouse model exhibits enhanced mammary tumor development with deficient ERα expression that confers tamoxifen resistance in vivo." (PMID 32934200, 2020). "Additionally, in ER (+) breast cancer cells, TET2 predominantly binds to ER enhancer element sites, indicating that TET2 recruitment may depend on cell-specific factors." (PMID 39201247, 2024). "Similarly, an alternative promoter of the TET2 gene was also reported in different tissues and cell lines including breast cancer cells although the biological significance of the new isoform remains unclear." (PMID 34885145, 2021). "Since dozens of transcription factors have been identified to recruit TET2 to specific gene loci for epigenetic regulation in different types of tissues, we speculate that a specific transcription factor may be responsible for this task in breast cancer." (PMID 34064441, 2021). "Given that anti-PD-1/L1 immunotherapy has been widely used in clinics, we speculate that the combination of HDAC inhibitors and targeting TET2 with anti-PD-L1 immunotherapy may be a new strategy for breast cancer patients who have low responsiveness to anti-PD-1/L1 immunotherapy." (PMID 34064441, 2021). "Moreover, TET2 may suppress breast cancer stem cells (CSC) through the regulation of the miRNA200c/PKCζ axis." (PMID 34885145, 2021). "Both in vivo and in vitro tests show that TET2 and FOXP1 complex promotes the demethylation of ESR1, GATA3, and FOXA1, which are usually silenced in advanced breast cancer." (PMID 40014756, 2025). "Laurent and colleagues also analyzed gene expression data from a cohort of breast cancer patients and revealed that both TET1 and TET2 expression significantly decreased with tumor progression (p < 0.0001)." (PMID 40116537, 2025). "Interrogation of TCGA RNA-seq data from breast cancer samples supported the data obtained from MCF-7 cells, showing that PCDHA4 expression levels are positively correlated with TET2 expression in patients." (PMID 35351824, 2022). "By using siRNAs targeting all three TETs, expression of CTSD and CLN3 was shown to be specifically repressed by TET2 in MCF-7 and T47D breast cancer cells and, to a lower extent, in HEK293T kidney cancer cells." (PMID 35351824, 2022). "We also analyzed the correlation between TET2 and PD-L1 by separating the CCLE breast cancer cell lines into three tumor subtypes and found that TET2 expression is negatively correlated with PD-L1 expression in luminal subtype (p = 0.0282)." (PMID 34064441, 2021). "Dysregulation of the TET2/5hmC pathway promotes epithelial–mesenchymal transition (EMT), chemotherapy resistance, proliferation, invasion, and metastasis during breast cancer pathogenesis." (PMID 34064441, 2021). "In breast cancer KDM2A interacts with RelA and acts on the promoter of TET2, inhibiting TET2 expression." (PMID 33805247, 2021). "In human estrogen-receptor positive breast cancer cells, BPA represses TET2 expression, reduces TET2 protein production and decreases DNA hydroxymethylation, indicating the involvement of the epigenetic pathway in the BPA-mediated tumor cell proliferation." (PMID 32370155, 2020). "Taken together, we demonstrate for the first time that TET2 is a direct repression target of KDM2A and reveal a novel mechanism by which KDM2A promotes DNA methylation and breast cancer progression via the inhibition of a DNA demethylase." (PMID 28785073, 2017).
breast carcinoma (continued). "In vitro studies revealed that cell migration and invasion are inhibited in breast cancer cells null for the oncogene lysine‐specific demethylase 2A (KDM2A), via TET2‐mediated activation of the downstream tumor suppressors E‐cadherin and epithelial cell adhesion molecule (EpCAM)." (PMID 40116537, 2025). "In breast cancer, KDM2A can promote DNA methylation by inhibiting the expression of tet-eleven translocation 2 (TET2), thereby suppressing the expression of epithelial cell adhesion molecule (EpCAM) and E-Cadherin, further enhancing the tumor invasion capacity of breast cancer." (PMID 37821959, 2023). "TET2-mediated oxidation of 5-methylcytosine establishes an antiviral state and contributes to MYC-dependent down-regulation of genes involved in lysosome biogenesis and function in breast cancer cells." (PMID 35351824, 2022). "As an example of TET2 CD–mediated gene activation, a subset of TSS-CGIs from the breast cancer-methylated PDCHA locus selectively gained H3K4me3 in TET2 CD cells in correlation with the activation of the associated genes as shown for PCDHA4, PCDHA3, PCDHA9, and PCDHA10." (PMID 35351824, 2022). "SNIP1-TET2 interaction enhances the ability of TET2 to trans-activate c-MYC target genes, ultimately promoting anchorage-independent cell growth and cisplatin resistance of MCF-7 breast cancer cells." (PMID 35449131, 2022). "In breast cancer, TET2 knockout results in an increase in m5C of most enhancers and a significant reduction in of H3K4me1 and H3K27ac enrichment, which jointly promoted the tumorigenesis of ERα-positive MCF7 breast cancer cells." (PMID 35371346, 2022). "In a similar manner, TCGA data analysis also showed that TET2 expression levels had a negative correlation with PD-L1 expression levels in breast cancer (n = 1904, p = 0.0065)." (PMID 34064441, 2021). "It has been reported that the absence and mutation of TET2 occurred in hematic tumors, and the lack of TET2 increased the stemness and metastasis of breast cancer cells." (PMID 34019487, 2021). "miR-22-3p also promotes breast cancer cells stemness through suppressing TET1 and TET2." (PMID 34019487, 2021). "Conversely, our recent work revealed that TET2 represses the expression of the PD-L1 gene in breast cancer either in the presence or absence of IFN-gamma treatment." (PMID 34885145, 2021). "Through an analysis of the four subtypes of TCGA breast cancer data, we found that TET2 and PD-L1 showed a negative correlation only in luminal B and Her2-enriched subtypes." (PMID 34064441, 2021). "Recent study reports that 5-hmC level is decreased in metastatic tissues of nasopharyngeal carcinoma, breast cancer, and colon cancer, compared with non-metastasis tumor tissues, and TET2 is involved in the process of tumor metastasis." (PMID 32774157, 2020). "To further determine the role of TET2 in conferring endocrine resistance in human breast cancer cells, we generated a stable TET2 knock-out cell line using the CRISPR-Cas9 system in ERα-positive, luminal breast cancer MCF7 cells." (PMID 32934200, 2020). "In contrast to nontumorigenic MCF12A and non-invasive breast cancer cell line T47D, TET2 was predominantly localized in the cytoplasm in aggressive triple-negative breast cancer cell line MDA-MB-231, which is deficient in endogenous RARβ expression." (PMID 31590252, 2019). "We thus chose to ectopically express TET2 in breast cancer cells and transfected MCF-7 cells with an expression vector for the Flag-tagged active murine TET2 CD and as controls, with a catalytically dead mutant (H1304Y and D1306A) TET2 mCD or an empty vector (EV)." (PMID 35351824, 2022). "Finally, we experimentally (i) confirmed the effect of FOXA1 expression on DNA methylation patterns at regions bound by FOXA1 in the MCF-7 breast cancer cell line, and (ii) detected interactions of FOXA1 with TET1 and TET2 proteins both in an in vitro setup and at endogenous levels." (PMID 35440061, 2022).
breast carcinoma (continued). "Furthermore, analysis of the CCLE and TCGA data showed a negative correlation between TET2 and PD-L1 expression in breast cancer." (PMID 34064441, 2021). "Interestingly, by analyzing multiple cancer cell lines from CCLE, we noticed that the correlation between TET2 and PD-L1 in lung cancer cell lines is also negative and more significant than that in breast cancer cell lines." (PMID 34064441, 2021). "However, our data showed that the PD-L1 promoter of breast cancer cells is in a DNA hypo-methylated status and that TET2 depletion does not alter the DNA methylation or hydroxymethylation levels at the promoter region of PD-L1 gene." (PMID 34064441, 2021). "Consistently, we observed an inverse correlation between PD-L1 and TET2 expression levels regardless of whether the breast cancer cell lines were cultured in vitro (CCLE data) or in cancer samples from patients (TCGA data)." (PMID 34064441, 2021). "Breast cancer patients did not significantly differ from control group in terms of TET1, TET2, and TDG mRNA expression." (PMID 38499584, 2024). "Expression of TET2 occurs in the nontumorigenic mammary epithelial cell line MCF12A and also in the non-invasive breast cancer cell line T47D, but repression occurs in aggressive breast cancers." (PMID 31590252, 2019).
glioma (35 papers, 2013 to 2025). A benign or malignant brain and spinal cord tumor that arises from glial cells (astrocytes, oligodendrocytes, ependymal cells). "A similar study showed that the decrease of TET2 (ten-eleven translocation 2), implicated in tumor suppression in multiple cancers, is frequent in gliomas." (PMID 32309604, 2018). "Kim and colleagues examined low-grade gliomas with wild-type IDH1/2 for mutations in or hypermethylation of TET2." (PMID 24202321, 2013). "In addition, there are other missense somatic mutations that are present in glioma in TET2 outside the catalytic domain." (PMID 36989121, 2023). "The reduction in TET2 expression is associated with an increase in glioma invasion and growth." (PMID 33805247, 2021). "The deficiency of TET2 induced a similar methylome with that IDHmt does in glioma." (PMID 33842477, 2021). "Whereas, the level of TET2 was significantly increased in plasma samples derived from patients with Grade II gliomas compared to controls (p < 0.01)." (PMID 35494033, 2022). "The most promising results were provided by TET2 gene that was significantly increased in Grade II glioma." (PMID 35494033, 2022). "Together, our results and previous findings indicate that, among the PRLMGs, SLC16A1 and TET2 are potentially important targets for intervention of glioma lactate metabolism that deserve priority in future investigation." (PMID 36203434, 2022). "In summary, ATRX was upregulated by DNA demethylation mediated by STAT5b/TET2 complex in TMZ resistant glioma cells." (PMID 32194873, 2020). "Loss of nuclear localization of TET2 has also been reported to occur in colorectal cancer and of TET1 in gliomas." (PMID 30045709, 2018). "This study also showed that ZEB1 is increased in gliomas and positively correlates with progression and inversely correlates with TET2 expression." (PMID 32309604, 2018). "TET2 mutations in various myeloid cancer, or mutations of IDH1 and IDH2 in low-grade gliomas, which can inhibit DNA hydroxymethylation by TET enzymes, have been reported and cause DNA hypermethylation phenotype." (PMID 27829228, 2016). "Other mechanisms of dioxygenase inhibition were also reported in gliomas, e. g. hypermethylation of the TET2 promoter." (PMID 27145078, 2016). "Müller and colleagues investigated levels of 5-hmC and the expression of TET1 and TET2 in glioma tissues and cell lines." (PMID 24202321, 2013). "Considering loss of 5-hmC is most prominent in high-grade gliomas, it is possible that silencing of TET2 by DNA methylation would have been found more frequently in higher grade gliomas." (PMID 24202321, 2013). "TET2 mutations are rare in glioma and neither Tet2 nor IDH1 knockout mice spontaneously generate brain tumors." (PMID 37528157, 2023). "EBF1 interacts with TET2 in multiple cancers like glioma, AML, and chondrosarcoma." (PMID 33805247, 2021). "Four of the IEAA-associated SNPs (rs2736100 in TERT, rs2275558 in PBX1, rs144317085 in TET2, and rs2492286 in RPN1) were associated with 16 unique traits including multiple cancers (e.g., lung cancer, glioma) and blood cell counts (e.g., platelet count, eosinophil count, red blood cell count)." (PMID 34187551, 2021). "Our results indicated that ATRX was upregulated via DNA demethylation mediated by STAT5b/TET2 complex in TMZ resistant glioma cells and that ATRX promoted PARP1 stabilization through down-regulating FADD by suppressing of H3K27me3 enrichment in FADD promoter region." (PMID 32194873, 2020). "Here we show that epigenetic mechanisms might play an important role in the aberrant regulation of TET2 in human glioma." (PMID 29899831, 2018). "We found a decrease in H4K16ac in the tumoral sample, further supporting the idea that, in addition to DNA methylation and DNA hydroxymethylation, histone post-translational modifications could have an important role in TET2 regulation in glioma." (PMID 29899831, 2018).
glioma (continued). "To identify other possible epigenetic mechanisms involved in TET2 regulation, we carried out quantitative ChIP analyses on brain and glioma samples using an antibody against H4K16 acetylation, a histone post-translational modification associated with gene activation." (PMID 29899831, 2018). "In addition, all six glioblastoma cell lines examined showed nuclear exclusion of TET1, whereas TET2 was detected in the nuclei of all glioma samples and cell lines." (PMID 24202321, 2013). "Although they found no mutations in TET2, they identified promoter methylation of TET2 in 5 of 35 low-grade gliomas, whereas low-grade gliomas with IDH1/2 mutations showed no hypermethylation of the TET2 promoter." (PMID 24202321, 2013). "However, significant overexpression of TET2 in Grade II gliomas might offer a new tool for effective diagnosis of lower-grade glioma patients." (PMID 35494033, 2022). "Thus, in glioma, TET2 mutations have not been described; however, TET2 promoter methylation has been detected in 14% of low-grade glioma patients without IDH mutation." (PMID 35386689, 2022). "However, reductions in TET2 expression and activity are unlikely to be due to TET2 mutations, as direct sequencing of TET2 revealed very few mutations and minimal association of mutations with levels of 5-hmC in gliomas." (PMID 33842321, 2021). "Therefore, it is unlikely that lower TET2 expression in glioma is transpiring as a result of promoter methylation-mediated transcriptional suppression, but may be an effect of transcription prevention due to intragenic DNA methylation." (PMID 33842321, 2021). "Transcription of TET2 may be repressed by zinc finger E-box-binding homeobox 1 (ZEB1) in gliomas." (PMID 33842321, 2021). "None of the IDH1/2 mutated gliomas had methylation of the TET2 promoter." (PMID 23998913, 2013). "Their downregulation was significantly higher in Grade IV GBM in comparison with Grade II gliomas (TET1 and TET3 p < 0.001, TET2 p < 0.01) and Grade III gliomas (TET1 p < 0.001, TET2 and TET3 p < 0.01)." (PMID 35494033, 2022). "Quantitative real-time PCR was performed to examine the mRNA expression of TET family genes (TET1, TET2, and TET3) in 34 samples, including 6 Grade II gliomas, 7 Grade III gliomas and 21 Grade IV GBM." (PMID 35494033, 2022). "We show that the miR-10b-5p onco-miR is induced by SOX2, directly targets TET2, mediates onco-methylation, GSC induction and glioma malignancy." (PMID 35136034, 2022). "Based on the patient-derived glioma stem cells (GSCs) model, the transcription factor (SOX2)-oncomiR (miR-10b-5p)-TET2 axis was identified, which plays an important role in promoting GBM oncogenesis." (PMID 35494033, 2022). "TET1 expression is upregulated in glioblastomas, TET2 is downregulated in gliomas, and TET3 is epigenetically repressed in gliomas." (PMID 33461542, 2021). "ZEB1 levels were inversely correlated with TET2 levels in tumors, and physical binding of ZEB1 to the TET2 promoter in glioma cells was observed in vitro." (PMID 33842321, 2021). "In comparison to normal human brain tissue, TET2 gene and protein expression is reduced in GBM and other gliomas." (PMID 33842321, 2021). "TET1 is elevated in GBM, while TET2 expression is downregulated in glioma, and TET3 is epigenetically repressed in glioma." (PMID 32244981, 2020). "In addition, TET2 promoter methylation, but not TET2 mutations, may represent an alternative mechanism of pathogenesis in low-grade gliomas lacking IDH1/2 mutations." (PMID 29849955, 2018). "Real-time RT-PCR analysis of 54 glioma samples showed that TET1 and TET2 mRNA was expressed at varying levels in primary glioblastomas, secondary glioblastomas, and anaplastic astrocytomas." (PMID 24202321, 2013). "This is supported by previous observations of reduced TET2 expression in gliomas without IDH or TET gene mutations, with promoter methylation of the TET2 gene proposed as an alternative mechanism for TET2 dysfunction." (PMID 41290745, 2025).
glioma (continued). "We found that TET1, TET2, TET3 mRNA, and 5-hmC levels were decreased during glioma grades." (PMID 35494033, 2022). "Bearing in mind that DNA-hypermethylation is often a result of an imbalance of DNA methylation and demethylation which can be based on reduced TET1 protein activity as shown in gliomas, we investigated the protein levels of TET1 and TET2 via immunohistochemistry." (PMID 33917711, 2021). "In glioma, ZEB1 binds to the TET2 promoter repressing its expression." (PMID 33805247, 2021). "In another study, hypermethylation of TET2 promoter was observed in a small fraction (16%) of low-grade diffuse gliomas without IDH mutation, but this phenomenon did not occur in gliomas with IDH mutation." (PMID 33842477, 2021). "TET2, as an interaction partner of the transcription factor EBF1, regulates DNA methylation in gliomas 44, STAT5b also could recruit TET2 in specific site to promote DNA demethylation." (PMID 32194873, 2020). "A low TET2 level in MA cells could be due to low gene dosage, but could also involve other mechanisms such as repression by ZEB1 as reported in glioma; MA cells express a high level of ZEB1 as a part of their EMT program." (PMID 31217902, 2019). "For instance, the reduction of TET2 enzyme levels by promoter methylation in absence of TET2 mutation was reported recently in low-grade diffuse astrocytomas, suggesting that this represents an additional pathomechanism in IDH1- and IDH2-mutated low-grade gliomas." (PMID 39090080, 2024). "Gliomas show lower TET expression independent of TET mutations, and we hypothesize that ascorbate may compensate for lower TET expression by upregulating residual TET2 function as was observed in a case study of acute myeloid leukemia." (PMID 33842321, 2021). "That suppression of TET2 and TET3 in GSC6 leads to attenuated proliferation under conditions of DNA damage suggests that they play a direct role in modulating the DNA damage response process and may contribute to the chemo−/radio-resistance of glioma stem cells." (PMID 29587824, 2018).